GCG (glucagon)
Diseases named in the same sentence as GCG in open-access papers (continued):
Sharing a sentence is not in itself a finding about the gene and the disease.
diabetes (continued). "In conclusion, glucagon secretion was not suppressed after the ingestion of a mixed meal in diabetes patients, and patients with poorer glycemic control showed a greater increase in postprandial glucagon levels." (PMID 34199839, 2021). "Based on the 13C HP spectra, it is possible to arrive at a simple metric that distinguishes the high gluconeogenic states (such as in diabetes or glucagon administration) from non-gluconeogenic livers using HP DHA as a substrate." (PMID 34357335, 2021). "It was recognised that islet cells in diabetes were not atrophic, as previously thought, but “pseudo-atrophic” containing glucagon- and somatostatin-containing cells, in addition to atypical regeneration with pancreatic-polypeptide-containing cells." (PMID 34083567, 2021). "On the other hand, linagliptin, empagliflozin and combination therapy did not alter serum insulin and glucagon levels in both an early and advanced phase of diabetes." (PMID 34373487, 2021). "Islets immunostained with anti-insulin and anti-glucagon antibodies showed that their number per area of the pancreas (islet density) was similar between the vehicle-treated groups and reduced (P<0.0001) in STZ-induced diabetes." (PMID 33746901, 2021). "After ingesting a meal, healthy adults show increased insulin secretion and suppressed glucagon secretion, whereas people with diabetes do not show suppression of glucagon secretion." (PMID 34199839, 2021). "Important evidence for this was the demonstration that subjects with T2DM had higher baseline glucagon levels than subjects without diabetes, and these levels were not suppressed by a carbohydrate meal, as was the case in subjects without diabetes." (PMID 33758717, 2021). "In the past, long diabetes duration was considered a prerequisite for the lack of glucagon response to occur but mounting evidence suggest that it often occurs as early as the first months to years after the diagnosis of type 1 diabetes." (PMID 34405569, 2021). "During the 1980s, several authors showed that IN glucagon was not different from IM glucagon in resolving hypoglycemia in normal subjects and in adults and children with diabetes." (PMID 34638984, 2021). "The question remains as to why glucagon is abnormally elevated in patients with diabetes and does not lower in response to a carbohydrate load in these patients." (PMID 32964214, 2020). "In the current study, we here determined active GIP, GLP-1, and glucagon levels in type 2 diabetes mellitus (T2DM) subjects with or without DPP-4 inhibitor treatment to characterize the cell-based, receptor-mediated bioassays in comparison to immunoassays." (PMID 32390941, 2020). "The pathophysiology of type 2 diabetes mellitus (T2DM) is characterized by not only insulin resistance, but also the abnormal regulation of glucagon secretion, suggesting that antagonizing the glucagon-induced signaling pathway has therapeutic potential in the treatment of T2DM." (PMID 32215330, 2020). "In the present study, Rokumigan, Hachimijiogan, and Goshajinkigan significantly inhibited glucagon signaling, while the other Kampo drugs used for the purpose of the amelioration of diabetes-related conditions did not." (PMID 32215330, 2020). "Second, parents perceived lack of staff education and training, such as for glucagon injections and in managing diabetes." (PMID 33233468, 2020). "Diabetes mainly developed due to lack of insulin release from the β cells and the abnormally high production of glucagon from the α cells of pancreas." (PMID 32815547, 2020). "The pancreatic islets regulate glucose metabolism through secretion of islet hormones such as insulin and glucagon, and INSM2 is a direct target of Ngn3 and NeuroD1, two crucial transcriptional factors involved in human diabetes and pancreatic islet development." (PMID 32511227, 2020). "Impairment of glucagon signaling helps to both prevent the occurrence of diabetes in conditions of near absence of insulin and increases the mass of α-cells." (PMID 32255979, 2020).
diabetes (continued). "During the following decade, several authors showed the efficacy of IN glucagon (drops, powders, and sprays) to resolve hypoglycemia in normal volunteers and in patients with diabetes, both adults and children." (PMID 31349701, 2019). "Interestingly, several peptides with different degrees of co-agonism for the glucagon and GLP-1 receptors were recently discovered, and are currently in clinical evaluation for the treatment of obesity and diabetes." (PMID 31337027, 2019). "In the Diabetes Surgery Study, we found a similar change in the insulin:glucagon molar ratio after RYGB, but no significant change after intensive medical management." (PMID 30755673, 2019). "Our earlier study showed that GIP transiently increases plasma glucagon levels as well as ISRs over the first 40 minutes of the graded glucose infusion and these responses were amplified by Xen only in subjects without type 2 diabetes mellitus." (PMID 29466430, 2018). "We observed no third-order interaction effects between diabetes, intervention and time for any of the measured biochemical parameters, except for glucagon." (PMID 29370144, 2018). "As it was presumed that diabetes as a comorbidity has a strong influence on the result of glucagon stimulation test, it was not included in the covariate." (PMID 30571730, 2018). "Despite the active search, a glucagon antagonist, which can be effective in treating diabetes, has not yet been found." (PMID 29670459, 2018). "In people without diabetes, developing hypoglycaemia leads to the suppression of endogenous insulin secretion (insulin ‘switch-off’) and a parallel rise in glucagon release from the pancreatic alpha cell." (PMID 29417183, 2018). "The design of our experiments was to mimic blood glucose volatility in diabetes in particular, and not in normal physiology, to investigate potential dynamic alterations in the glucagon interactome." (PMID 30713523, 2018). "In summary, administration of the SIRT1 activator, SRT3025, to mice with STZ-induced diabetes led to improved glycaemia with reductions in plasma glucagon and α cell hyperplasia without affecting either insulin secretion or ß-cell mass." (PMID 30228292, 2018). "As well as in this paper, Xen amplifies the effects of GIP on insulin, glucagon, and pancreatic polypeptide release during graded glucose infusions in humans without type 2 diabetes mellitus." (PMID 29466430, 2018). "Despite alpha-cell dysfunction in diabetes mellitus being well known in human subjects and rodents, there are no publications addressing Grx expression in glucagon-producing cells." (PMID 29593651, 2018). "Exercise increased fasting glucagon in the healthy control group but not in T2D (Exercise by Diabetes interaction, p = 0.02), whereas the postprandial iAUC for glucagon was reduced by exercise (main effect of Exercise, p = 0.01)." (PMID 28744255, 2017). "The importance of glucagon in diabetes is confirmed by the finding that mice lacking glucagon receptors remain normoglycemic even after complete destruction of β cells." (PMID 27117413, 2016). "Recently, some researchers have reported that mice that lack the receptor proteins through which glucagon works do not develop diabetes, even when they are treated with a drug called streptozotocin that wipes out most of their beta cells." (PMID 27092792, 2016). "This suggests that the high blood sugar levels seen in diabetes result from an excess of glucagon, and not a lack of insulin." (PMID 27092792, 2016). "Over a 3-month study period, a Palaeolithic diet resulted in reduced fasting plasma leptin levels, but did not change fasting levels of insulin, C-peptide, glucagon, incretins, ghrelin and adipokines compared to the currently recommended diabetes diet." (PMID 27216013, 2016). "Although Gcgr-/- mice developed diabetes upon massive β-cell ablation, lack of glucagon action reduced or normalized glycemia in conditions of less severe insulin deficiency." (PMID 27092792, 2016).
diabetes (continued). "Thus, to determine whether lack of glucagon signaling would also prevent hyperglycemia and diabetes in the context of a more severe insulin deficiency, we used a transgenic model of diphtheria toxin (DT)-mediated β-cell ablation, termed RIP-DTR, which leads to an almost complete β-cell elimination." (PMID 27092792, 2016). "Therefore, the role of glucagon and GLP-1 and their contribution to the pathophysiology of diabetes and obesity remain to be fully clarified." (PMID 26378455, 2015). "In the present study, we showed that in spite of a glucagon deficiency, HFD-fed Gcggfp/gfp mice did develop diabetes, which was due to impaired insulin secretion and not insulin resistance." (PMID 26378455, 2015). "This is supported by the fact that metabolic manifestations of diabetes cannot occur without glucagon action." (PMID 26909312, 2015). "Incretin-based therapies, the most recent therapeutic options for type 2 diabetes mellitus (T2DM) management, can modify various elements of the disease, including hypersecretion of glucagon, abnormal gastric emptying, postprandial hyperglycaemia, and, possibly, pancreatic β cell dysfunction." (PMID 26075286, 2015). "DM after TP means a complete lack of endogenous insulin and glucagon, leading to uncontrollable frequent and deep states of hypoglycemia with hyperglycemic episodes (brittle diabetes)." (PMID 25013768, 2014). "Although different thresholds for FCP and post-glucagon C-peptide (PGCP) have been used, most studies conclude that there is a high degree of concordance, ranging between 86 and 89% between C-peptide levels and type of diabetes." (PMID 25945127, 2014). "At an early stage of diabetes (1 week), the normal glucagon-somatostatin rim was absent, and α- and δ-cells were found at the center of the islet." (PMID 23762878, 2013). "In diabetes, glucagon secretion is not suppressed at high glucose, exacerbating the consequences of insufficient insulin secretion, and is inadequate at low glucose, potentially leading to fatal hypoglycemia." (PMID 24315372, 2013). "Recently, leptin has been shown to suppress glucagon and correct diabetes in mice, in the absence of insulin." (PMID 23132340, 2013). "If glucagon is essential for development of diabetes, one would have expected that total pancreatectomy would not induce diabetes." (PMID 22969729, 2012). "The defect of glucagon and epinephrine responses to hypoglycemia in diabetes is puzzling because both counterregulatory responses are normal or even excessive during some stresses, such as moderate and strenuous exercise, both in dogs and humans." (PMID 22969729, 2012). "Confining the analysis to those with long-standing diabetes (>20 years) (n=112), who are likely to be affected by impaired glucagon and catecholamine responses, did not alter the result (P=0.68)." (PMID 23781301, 2012). "Treatments designed to inhibit glucagon-GCGR interaction, such as GCGR antisense oligonucleotides, small-molecule GCGR antagonists, and GCGR-antagonizing antibodies, have demonstrated various benefits on diabetes in mice and primates." (PMID 21853126, 2011). "Moreover, in one study of 12 healthy male adults without diabetes, intact soya protein significantly elevated the two-hour area under the curve (AUC) of both insulin (p=0.018) and glucagon (p<0.001) compared to hydrolyzed soya protein." (PMID 41602572, 2026). "Notably, INS and GCG, levels were significantly decreased in donors with PDAC-associated diabetes compared to those with PDAC but no diabetes." (PMID 40244011, 2025). "Additionally, the integration of glucagon and GLP‐1 receptor signaling has improved diabetes management by promoting weight reduction without causing hyperglycemia." (PMID 40919135, 2025). "However, they stated that there had been no problems reaching the diabetes team whenever a need for an insulin or glucagon dose arose." (PMID 40310133, 2025).
diabetes (continued). "In this study, in which we directly compared hormonal and symptom responses to hypoglycaemia, we found that people with type 1 diabetes had blunted glucagon and adrenaline responses to hypoglycaemia compared to those with long-standing insulin-treated type 2 diabetes and those without diabetes." (PMID 38376580, 2024). "Increased alpha cell glucagon secretion in diabetes and lack of response to glucose levels has been attributed to the lack of inhibition of cAMP production by serotonin produced from beta cells, as cAMP increases baseline levels of glucagon secretion." (PMID 39594662, 2024). "We aimed to describe for the first time the localization and density of glucagon- (Glu+Cs) and insulin (Ins+Cs)-immunopositive endocrine cells in the wall of porcine DHC, DCH, DC, and VB for better understanding of the pathophysiology and treatment of diabetes." (PMID 38094502, 2023). "However, i.v. administration of glucose was reported to inhibit glucagon release similarly in people with or without diabetes." (PMID 37764697, 2023). "The response in glucose, glucagon and PYY was higher among participants with T2D, compared to participants with pre-T2D, with either pre-load (e.g. p-value for the multiplicative interaction between diabetes status and the swallowed pre-load was 0.01 for glucose and <0.001 for insulin)." (PMID 37624823, 2023). "However, high levels of glucagon can also be found in different non-neoplastic conditions, such as cirrhosis, diabetes mellitus, sepsis, and burns." (PMID 37685358, 2023). "Interestingly, despite the decrease in insulin content at day 15 of diabetes, islet morphology, insulin and glucagon staining were not affected in NDM islets." (PMID 35180212, 2022). "We did not determine whether the changes in glucagon secretion due to OMP are limited to STZ-induced hyperglycemia alone or diabetes in general, such as high-fat diet-induced hyperglycemia." (PMID 36104518, 2022). "Because the importance of glucagon in the pathogenesis of diabetes is becoming increasingly evident, it is even more urgent now to resolve lingering uncertainties and definitively establish glucagon’s true mechanism of glycemia regulation in health and disease." (PMID 35569125, 2022). "In addition, plasma glucagon did not significantly change during diabetes progression, and percent of α-cell area and gene expression of the α-cell marker Arx remained similar in NDM and littermate controls islets at day 15 of diabetes." (PMID 35180212, 2022). "In the first two studies, the effects of diabetes on plasma glucagon levels were not reported." (PMID 35569125, 2022). "In 1997, a survey showed that patients would have been enthusiastic on the idea that easily administered formulations would substantially expand the use of glucagon to prevent or to treat hypos, but a survey showed that 75% adult patients with diabetes did not carry a glucagon emergency kit." (PMID 36550552, 2022). "Persons with diabetes per one unit of glucagon were not different between the two Groups." (PMID 36550552, 2022). "In response to hypoglycemia, glucagon release may be blunted or absent in individuals with diabetes." (PMID 36992764, 2022). "Fasting glucagon was lower in nondiabetic women than men and was similar in diabetes." (PMID 34657182, 2022). "In addition, another recycling endosome marker, Rab11B, showed a similar distribution within the islet; it also did not colocalize with glucagon but colocalized with insulin; this pattern remained unchanged in diabetes." (PMID 34923907, 2022). "Even in adults without diabetes, hypoglycemia may blunt the overall hormonal response the next time it occurs to a certain extent, but their release of glucagon is not impacted." (PMID 36992764, 2022).
diabetes (continued). "Consistent with the possibility for SASP to alter α cell function in vivo, senescent β cells accumulate at higher levels in islets of autoantibody-positive donors compared to no diabetes controls and autoantibody-positive donor islets exhibit abnormally increased glucagon secretion." (PMID 36277717, 2022). "However, as patients with diabetes already have an elevated baseline of glucagon, adding SGLT2 inhibitors may further elevate glucagon levels in the blood." (PMID 33581735, 2021). "Given the potency of somatostatin in inhibiting glucagon and insulin secretion, it is not surprising that defects in δ-cell function and aberrant regulation of paracrine interactions play a fundamental role in the development of diabetes." (PMID 33494193, 2021). "In other words, blood glucose level increased 30 min after the ingestion of food in diabetes patients, but glucagon secretion was not suppressed; contrary to expectations, it may actually increase in patients with poor glycemic control." (PMID 34199839, 2021). "Ga = gastrin, Glu = glucagon, In = insulin, PP = polypeptide, SS = somatostatin, VIP = vasoactive intestinal peptide, DM = diabetes mellitus, RFA = radiofrequency ablation." (PMID 34118524, 2021). "Interestingly, insulinotropic but not glucagon static effects of GLP-1 are significantly reduced in patients with diabetes." (PMID 34577569, 2021). "In spite of preserved glucagon secretion after specific stimuli in adults with type 1 diabetes, the maximum glucagon secretory capacity of these individuals in head‐to‐head studies is reduced compared with matched individuals without diabetes." (PMID 34405569, 2021). "Our patient has not manifested any changes in blood glucose, glucagon, or insulin levels, but he may develop later‐onset diabetes." (PMID 32277595, 2020). "The hyperglycemia in type 2 diabetes mellitus (T2DM) results from an imbalance between insulin secretion and insulin sensitivity with impaired insulin action and an insufficient and delayed insulin response during meals as well as an inappropriate glucagon secretion." (PMID 31164926, 2019). "Animals with streptozotocin (STZ)-induced diabetes and preceding recurrent hypoglycemia regimens exhibited raised baseline GABA levels compared to controls, but also a restoration of counter-regulatory glucagon and epinephrine release after the administration of 4CIN and OX." (PMID 30696060, 2019). "Treatment of diabetes using the current GRAs may therefore not be feasible, however, one may speculate that targeted antagonism of glucagon signaling may circumvent these unwarranted side-effects." (PMID 31068828, 2019). "In their study, reversal of hyperglucagonemia by liraglutide or a glucagon-neutralizing antibody does not suppress increased hepatic gluconeogenic expression or improve blood glucose control but does attenuate ketosis in uncontrolled diabetes." (PMID 30369948, 2018). "It will be important to identify the neurotransmitters or neuropeptides that mediate the effects of Xen on insulin and glucagon release in humans because signaling pathways initiated by Xen rather than GIP fail early during the development of type 2 diabetes mellitus." (PMID 29466430, 2018). "Similarly, Xen infusion increased the postprandial pancreatic polypeptide response 6-fold in humans with normal glucose tolerance, impaired glucose tolerance, and type 2 diabetes mellitus without affecting ISRs or plasma glucagon levels." (PMID 29466430, 2018). "For many years, it was tacitly accepted that glucagon might play a role, but that the lack of insulin was believed to be the predominant hyperglycemic factor in diabetes, and this remained textbook dogma." (PMID 28323959, 2017). "GcgKO mice developed severe diabetes by hSTZ administration despite the absence of glucagon." (PMID 27053237, 2016).